RN7SKP232 (RN7SK pseudogene 232)
Gene: Miscellaneous RNA gene on chromosome 5 (151,704,289 to 151,704,578, reverse strand). Ensembl gene ENSG00000222102.
Homologues: Orthologues: chimpanzee 7SK (94% identical). Paralogues in human: 7SK (77% identical), RN7SKP176 (75% identical), RN7SKP255 (74% identical), RN7SKP9 (74% identical), RN7SKP80 (74% identical), RN7SKP204 (73% identical), RN7SKP37 (73% identical), RN7SKP189 (73% identical), RN7SKP230 (73% identical), RN7SKP102 (73% identical), RN7SKP180 (73% identical), RN7SKP203 (73% identical), and 284 more.